FGF14 (fibroblast growth factor 14)
Diseases named in the same sentence as FGF14 in open-access papers (continued):
Sharing a sentence is not in itself a finding about the gene and the disease.
ovarian carcinoma (1 paper, 2020). A malignant neoplasm originating from the surface ovarian epithelium. "In addition to an increased expression, some genes were also downregulated by the overexpression of FGF14, such as COL11A1 which encodes the α1 chain of collagen XI and MUC16, a well-established biomarker used to monitor the progression and recurrence of ovarian cancer." (PMID 32707902, 2020).
pituitary adenomas (1 paper, 2023). "The expression levels of ANXA2, PMAIP1, SPRY2, C2CD4A, APOD, FGF14 and FKBP10 were significantly upregulated while FNDC5 and MAP3K4 were downregulated in the invasive gonadotrophic pituitary adenomas compared to the non-invasive ones." (PMID 36750863, 2023).
squamous cell carcinoma (1 paper, 2020). A carcinoma arising from squamous epithelial cells. "While FGF14 expression was less in some LUAC cell lines (A549, H838, H1299, and H1650), it differed in squamous cell carcinoma (LUSC) cell lines (H226 and H520)." (PMID 32707902, 2020).
trigeminal neuralgia (1 paper, 2025). Trigeminal neuralgia is a nerve disorder that causes a stabbing or electric-shock-like pain in parts of the face. "These cases highlight, that SCA27A can be episodic, and expand the phenotypic spectrum of FGF14 structural variants to include trigeminal neuralgia." (PMID 41099962, 2025). "We review potential mechanism from pre-clinical studies relating FGF14 haploinsufficiency to cerebellar, cognitive, neuropsychiatric symptoms, as well as trigeminal neuralgia." (PMID 41099962, 2025).
tumor (16 papers, 2018 to 2025). "Therefore, we speculate that the tumor-promoting process of miR-1246b may be caused by the activation of ERK after binding to FGF14." (PMID 38040694, 2023). "This cluster was enriched in genes involved in differentiation and developmental processes (for example, SOX1 and SOX9, HOXD3 and HOXD8, and TBX4) and genes implicated as tumor suppressors (for example, SOX1 and SOX17, TSHZ3, WT1-AS, and FGF14)." (PMID 40931149, 2025). "Transwell experiments also suggested that compared with that in the control group, the number of tumor cells passing through the chamber was significantly increased after FGF14 expression was inhibited." (PMID 38040694, 2023). "Further in vitro studies suggested that FGF14 inhibited the proliferation and invasion of tumor cells by inhibiting ERK phosphorylation." (PMID 38040694, 2023). "The upregulation of FGF14 in tumor cells can antagonize the tumor growth-promoting effect of miR-1246b." (PMID 38040694, 2023). "FGF14AS2 inhibits tumour progression in many ways, such as inhibiting metastasis by regulating the miR-370-3p/FGF14 axis." (PMID 36844873, 2023). "In this study, we first illustrated that FGF14 was downregulated in CRC tumor tissues and cell lines, which is probably attributed to promoter methylation of FGF14." (PMID 31949485, 2020). "Both, the 27 k and 450 k Illumina Methylation Assay data sets showed a significant increase of FGF14 DNA-methylation in LUAC samples compared with non-tumor tissue." (PMID 32707902, 2020). "The results from the in vivo model provided further evidence of the tumor-suppressive role of FGF14." (PMID 31949485, 2020). "In conclusion, FGF14 is a novel tumor suppressor, which suppresses cell proliferation and induces cell apoptosis via mediating PI3K/AKT/mTOR pathway." (PMID 31949485, 2020). "The tumor suppressive effect of FGF14 was correlated to the inducement of apoptosis, as proved in FGF14-expressing CRC cell lines and xenografted tumors in the nude mice." (PMID 31949485, 2020). "We further proved the direct effect of tumor cell functional changes due to FGF14 overexpression and were able to abrogate the suppressive properties of FGF14 by siRNA treatment of the NSCLC cells." (PMID 32707902, 2020). "The high frequency of FGF14 silencing in both CRC cell lines and tissues suggests a tumor-suppressive role of FGF14 in CRC tumorigenesis." (PMID 31949485, 2020). "We found that FGF14 expression at mRNA and protein level was significantly reduced compared with samples from non-tumor or healthy donor lung tissue." (PMID 32707902, 2020). "In contrast with the human samples, ADARB1 and CCBE1 were upregulated and COL11A1 and MUC16 were downregulated in FGF14 overexpressing xenograft tumors, which emphasized the tumor suppressing role of FGF14 in NSCLC." (PMID 32707902, 2020). "From the time of inoculation, the tumor volume over time showed decreased tumor progression in FGF14 OE cells injected animals." (PMID 32707902, 2020). "Chromatin immunoprecipitation sequencing identified that ZNF750 directly regulated FGF14 (encoding fibroblast growth factor 14), ablation of which reversed ZNF750’s tumor repressor effect." (PMID 30518868, 2018). "Overexpression of ZNF750 blocked tumor cell growth in vitro and in vivo, while FGF14 functions as the downstream target of ZNF750 to regulate NPC apoptosis." (PMID 30518868, 2018). "Immunohistochemical results indicated that the expression of FGF14 was reduced in tumor tissues with high miR-1246b expression, indicating that miR-1246b could promote tumor proliferation by downregulating the expression of FGF14." (PMID 38040694, 2023). "Therefore, FGF14 is a novel tumor suppressor that functions by regulating the PI3K/AKT/mTOR pathway to inhibit cell growth and induce apoptosis." (PMID 37108717, 2023). "In contrast, the upregulation of miR-1246b could decrease the expression of FGF14 and ultimately enhance the proliferation, migration and invasion of tumor cells by activating ERK and EMT." (PMID 38040694, 2023).
tumor (continued). "Moreover, FGF14 overexpressing tumor cell RNA sequencing data suggests that genes affected by FGF14 were related to the extracellular matrix, playing a role in proliferation and migration." (PMID 32707902, 2020). "We further demonstrated that FGF14 might act as a tumor suppressor which inhibited cell growth and induced cell apoptosis of CRC through mediating PI3K/AKT/mTOR signaling pathway." (PMID 31949485, 2020). "Third, FGF14 overexpression reduces tumor progression in subcutaneous tumors in vivo." (PMID 32707902, 2020). "In conclusion, the data reported here provided strong support to the concept that reduced or silenced expression of FGF14 is modulated by DNA methylation of this gene, and FGF14 functions as a novel tumor suppressor, which induces cell apoptosis via inhibiting PI3K/AKT/mTOR signaling." (PMID 31949485, 2020). "In xenograft mouse model, overexpression of FGF14 significantly reduced tumor growth (P<0.001)." (PMID 31949485, 2020). "We observed low or silenced expression of FGF14 in both CRC tumor tissues and cell lines, accompanying promoter methylation of FGF14, suggesting that promoter methylation might be the predominant mechanism for the inactivation of FGF14 in CRC." (PMID 31949485, 2020). "Moreover, chromatin immunoprecipitation sequencing (ChIP-Seq) identified fibroblast growth factor 14 (FGF14) as the downstream target of ZNF750, and blocking FGF14 reversed the tumor repressor effect of ZNF750 in NPC cells." (PMID 30518868, 2018). "Moreover, the inhibition of NPC tumor growth in mice after ZNF750 overexpression was reversed by FGF14 knockdown." (PMID 30518868, 2018). "However, the growth and colony formation abilities of NPC cells were significantly reduced, supporting the view that FGF14 acts as a tumor repressor in NPC." (PMID 30518868, 2018). "We then asked whether inhibiting FGF14 would reverse the tumor repressor function of ZNF750 in vitro and in vivo." (PMID 30518868, 2018). "Additionally, FGF14 overexpression dramatically decreased tumor growth in a xenograft mouse model." (PMID 37108717, 2023). "FGF13 and FGF14 might be tumour suppressors in breast cancer." (PMID 35193394, 2022). "Notably, we could detect FGF14 overexpression in the tumor tissue after 40 days of tumor growth at the mRNA and protein level." (PMID 32707902, 2020). "Therefore, the targeting of FGF14 may provide new therapeutic approaches in terms of tumor growth inhibition, supported by the following findings." (PMID 32707902, 2020). "Therefore, newly established inhibitors targeting the tumor suppressive properties of FGF14 would be a promising therapeutic strategy for LUAC patients and need further investigation to identify the underlying molecular mechanisms, thereby enabling the development of new therapeutic options." (PMID 32707902, 2020). "Investigating these classical markers in our data, we did observe a statistically significant increase of TNF (TNF‐α) in G1 tumors, FGF14 in G2 tumors, and FGF8, FGF18, and PDGFA in G3 tumor in comparison to pancreatic islet cells." (PMID 39245631, 2025). "Conversely, ZNF750, a tumor suppressor in NPC, is destabilized by METTL3-mediated m6A modification, leading to reduced FGF14 expression and diminished apoptosis-promoting effects." (PMID 39695216, 2024). "Paradoxically, a group of proteins, including C1QL3, EPB41, SNX10, FGF14, GLB1L2 and TRAK2, have been reported as good prognostic markers or tumor suppressors in the NmFMC group." (PMID 38951817, 2024). "Mechanistically, ZNF750 has been reported to mediate tumor-suppressive roles by regulating the expression of various downstream genes, such as TINCR, LAMC2, DANCR, FGF14, and SNAI1." (PMID 37365152, 2023). "The overexpression FGF7, FGF9, FGF14, FGF18 and IGF1 genes was found significant in early tumor grades." (PMID 34061869, 2021).
tumor (continued). "Our findings identified FGF14 as the direct target gene of ZNF750, and the ZNF750-FGF14 signaling axis inhibited NPC growth through promoting cell apoptosis, which broadened our understanding of ZNF750 in repressing tumor development." (PMID 30518868, 2018). "Furthermore, overexpression of FGF12, FGF14, FGF17, FGFR1, FGFBP3 and IGFBPL1 genes was found in early tumor stage, while, overexpression of IGF1R, IGF2BP2 and INSRR was found in advanced tumor stages." (PMID 34061869, 2021). "Therefore, we deduced that miR-1246b may promote tumor development by ERK and EMT alterations through FGF14." (PMID 38040694, 2023).
cancer (11 papers, 2017 to 2025). A tumor composed of atypical neoplastic, often pleomorphic cells that invade other tissues. "The top 10 frequently affected cancer-associated genes are HIRA (OG), CSMD1 (TS), CDH13 (TS), PRRX1 (OG), FHIT (TS), MGAM (OG), TBL1XR1 (OG), RHOA (OG), FGF14 (TS), and CNTNAP2 (TS)." (PMID 35013466, 2022). "The induction of mesenchymal to epithelial transition (MET) by reprogramming the malignant phenotype of the cancer cell seems to be induced by overexpression of FGF14." (PMID 32707902, 2020). "Moreover, we validated FGF14 expression in several cancer cell lines, breast (MCF-7), prostate (DU145, PC3) ovary (SKOV3, OVCAR3), liver (HEP2G), pancreatic (MiaPaCa-2, Capan-1), and colon (Colo320, SW480), revealing a substantial variability." (PMID 32707902, 2020). "Although FGF14 in particular is not implicated in cancer, aberrant signaling of other Fibroblast Growth Factors are widely found in the pathogenesis of cancer." (PMID 30557297, 2018). "Key cancer-related transcripts were identified, such as CLDN1, TP63, FGF14, DDX60 and DRAM." (PMID 32839509, 2020).
brain disorder (5 papers, 2015 to 2025). A disease affecting the brain or part of the brain. "There are several studies on FGF14 in regard to brain disorders; it is known to interact with voltage gated sodium channels." (PMID 32707902, 2020). "The goal of this Mini Review article is to provide a summary of studies on the emerging role of FGF14 in complex brain disorders." (PMID 28469558, 2017).
neurodegenerative disease (5 papers, 2020 to 2025). A disorder of the central nervous system characterized by gradual and progressive loss of neural tissue and neurologic function. "GAA-FGF14 disease/spinocerebellar ataxia 27B is a recently described neurodegenerative disease caused by (GAA)≥250 expansions in the fibroblast growth factor 14 (FGF14) gene, but its phenotypic spectrum, pathogenic threshold, and evidence-based treatability remain to be established." (PMID 38507876, 2024). "Collectively, our findings reinforce the pathogenic size threshold of ≥300 repeats and establish a foundation for future studies investigating the role of FGF14 in neurodegenerative diseases." (PMID 40894141, 2025). "A study in 2023 has identified a new type of TNR expansion neurodegenerative disease, late-onset cerebellar ataxia (LOCA), also named GAA-FGF14 ataxia/spinocerebellar ataxia 27B, that is caused by GAA/TTC repeat expansion at intron 1 of the fibroblast growth factor 14 (FGF14) gene." (PMID 39062522, 2024).
neurological disorders (5 papers, 2020 to 2025). "Of particular interest here was a high fraction of cases with long expansions in the FGF14 STR region, which was only recently characterized as a common cause of neurological disorder partially overlapping RFC1-related phenotypes." (PMID 40141365, 2025). "Using immunohistochemistry, we confirmed a significant decrease in VGAT in the PFC of fgf14−/− mice, confirming a key role of FGF14 in brain areas associated with the cognitive domain in the context of psychiatric and neurological disorders." (PMID 32112487, 2020).
peripheral neuropathy (4 papers, 2024 to 2025). A disorder affecting the peripheral nervous system. "From the available data, it does not appear that repeat expansions in FGF14 present with peripheral neuropathy unlike CANVAS syndrome." (PMID 39083076, 2024).
movement disorder (3 papers, 2007 to 2025). Neurological conditions resulting in abnormal voluntary or involuntary movement, which may impact the speed, fluency, quality and ease of movement. "Deficits in fgf14 are associated with the development of movement disorders and it is well established that early exposure to organophosphates compromises the subsequent development of motor activity." (PMID 17589599, 2007).
psychiatric disorder (3 papers, 2016 to 2020). A disorder characterized by behavioral and/or psychological abnormalities, often accompanied by physical symptoms. "We provide new clinical and preclinical evidence for a significant psychiatric component in SCA27, strengthening the hypothesis of FGF14 as an important modulator of psychiatric disease." (PMID 32112487, 2020).
adenocarcinoma (1 paper, 2020). A common cancer characterized by the presence of malignant glandular cells. "Additionally, adenocarcinoma cell line A549, was a known KRAS mutated cell line and matches with data from patients with mutated KRAS, also showing FGF14 downregulation." (PMID 32707902, 2020).
infection (1 paper, 2023). The state of being infected such as from the introduction of a foreign agent such as serum, vaccine, antigenic substance or organism. "Furthermore, knockdown of FGF14 in CA1 reduced sickness behavior caused by infection." (PMID 38115011, 2023). "Hyperexcitability of CA1 pyramidal neurons caused by infection was mitigated via an anti-TNF antibody and genetic silencing of FGF14 in CA1." (PMID 38115011, 2023).
FGF14 also shares sentences with these, for which no sentence is quoted: cerebellar ataxia (23 papers); neuropathy (5); Tremor (5); Cerebellar atrophy (3); Anxiety (2); autism spectrum disorder (2); autosomal dominant cerebellar ataxia (2); bipolar disorder (2); Dysarthria (2); frontotemporal dementia (2); learning disabilities (2); neurodevelopmental disorder (2); Onset (2); Parkinsonism (2); Sensory neuropathy (2); Adult onset (1); amyotrophic lateral sclerosis (1); anxiety disorder (1); autosomal dominant disease (1); autosomal recessive disease (1); Cachexia (1); cardiac conduction disorders (1); cardiac hypertrophy (1); cerebellar degeneration (1); cerebral malaria (1); cervical cancer (1); cognitive disorder (1); colon cancer (1); dementia (1); dentatorubral-pallidoluysian atrophy (1).
A further 32 diseases each share a sentence with FGF14 in 1 paper.